FTCD (formimidoyltransferase cyclodeaminase)
Description:
Folate-dependent enzyme, that displays both transferase and deaminase activity. Serves to channel one-carbon units from formiminoglutamate to the folate pool. Binds and promotes bundling of vimentin filaments originating from the Golgi.
Synonyms: LCHC1
Tractability: Antibody: its Gene Ontology location is reachable by antibodies, with high confidence; the Human Protein Atlas places it where antibodies can reach. PROTAC: its protein half-life has been measured.
Gene: Protein-coding gene on chromosome 21 (46,136,083 to 46,155,581, reverse strand). Ensembl gene ENSG00000160282.
Subcellular location: Cytoplasm, cytosol; Golgi apparatus; Cytoplasm, cytoskeleton, microtubule organizing center, centrosome, centriole
Subcellular location (Human Protein Atlas): Cytosol; Plasma membrane
Pathways (Reactome):
Metabolism: Histidine catabolism
Gene Ontology:
Molecular function: glutamate formimidoyltransferase activity; microtubule binding; protein binding; formimidoyltetrahydrofolate cyclodeaminase activity; catalytic activity; folic acid binding; transferase activity
Biological process: folic acid-containing compound metabolic process; cytoskeleton organization
Cellular component: cytosol; extracellular exosome; Golgi membrane; smooth endoplasmic reticulum membrane; cytoplasm; endoplasmic reticulum; endoplasmic reticulum-Golgi intermediate compartment; Golgi apparatus; centriole
Genetic constraint (gnomAD): Loss-of-function variants: 69 observed, 52.35 expected, observed/expected ratio (o/e) 1.32, 90% interval 1.08 to 1.61. The synonymous counts are far from expectation, so gnomAD's model fits this gene poorly and the ratio says little. Missense variants: 785 observed, 642.87 expected, observed/expected ratio (o/e) 1.22, 90% interval 1.15 to 1.29. Synonymous variants: 366 observed, 287.94 expected, observed/expected ratio (o/e) 1.27, 90% interval 1.17 to 1.39.
Homologues: Orthologues: rat Ftcd (84% identical), mouse Ftcd (84% identical), pig FTCD (82% identical), guinea pig FTCD (81% identical), macaque FTCD (81% identical), dog FTCD (71% identical), tropical clawed frog ftcd (70% identical), zebrafish ftcd (66% identical). Paralogues in human: FTCDNL1 (6% identical).
Diseases named in the same sentence as FTCD in open-access papers:
FTCD is named in the same sentence as 25 diseases in open-access papers, as found by Europe PMC text mining. Sharing a sentence is not in itself a finding about the gene and the disease. The quoted sentences say what the papers report.
formiminoglutamic aciduria (4 papers, 2017 to 2024). Formiminoglutamic aciduria, in its moderate form and in the absence of histidine administration, is characterized by mild developmental delay and elevated concentrations of formiminoglutamate (FIGLU) in the urine. "These genes are linked with a range of X-linked and autosomal disorders, e.g., TMLHE (X-linked Autism), CDKL5 (Developmental Encephalopathy), FANCD2 (Fanconi anaemia), FLT4 (congenital heart defects), FTCD (Glutamate formiminotransferase deficiency), and DOCK8 (DOCK8 immunodeficiency syndrome)." (PMID 38033082, 2023). "Homozygous presence of the NM_001320412: c.530G > A, p.(Gly177Glu) variant in the FTCD gene leads to autosomal recessive glutamate formiminotransferase deficiency (OMIM: #229100) characterized by growth retardation, severe developmental delay and megaloblastic anemia." (PMID 29373990, 2018). "Thus, it is questionable whether congenital FIGLU‐uria due to FTCD deficiency is a condition of short‐term clinical concern." (PMID 29178637, 2017). "We observed additional FTCD alleles leading to urinary FIGLU elevations, and thus, providing molecular evidence of FTCD deficiency in cases identified by newborn screening or clinical biochemical genetic laboratory testing." (PMID 29178637, 2017). "Formiminoglutamic aciduria (OMIM #229100) is associated with an autosomal recessive condition affecting folate and histidine metabolism and often caused by formiminotransferase‐cyclodeaminase (FTCD, EC 2.1.2.5 to EC 4.3.1.4) deficiency, which is encoded by FTCD (HGNC: 3974; OMIM: 606806)." (PMID 29178637, 2017).
autoimmune hepatitis (3 papers, 2019 to 2021). Hepatitis caused by autoantibodies. "FTCD is abundantly expressed in human fetal and adult liver tissue and is associated with autoimmune hepatitis and glutamate formiminotransferase deficiency." (PMID 33380233, 2021). "FTCD, a liver-specific enzyme integrating Golgi complex with vimentin filament cytoskeleton, is linked to autoimmune hepatitis and glutamate formiminotransferase deficiency." (PMID 34276651, 2021).
hepatocellular carcinoma (3 papers, 2021 to 2023). A malignant tumor that arises from hepatocytes. "FTCD was found significantly downregulated in hepatocellular carcinoma (HCC) and served as a diagnostic biomarker for HCC." (PMID 34660806, 2021). "FTCD serves as an immunohistochemical tumor marker and is a candidate tumor suppressor in hepatocellular carcinoma (HCC)." (PMID 34941873, 2021). "FTCD, highly expresses in the liver, serves as a liver-specific autoantigen in patients with autoimmune hepatitis and a candidate tumor suppressor gene in hepatocellular carcinoma." (PMID 34941873, 2021). "created a novel Hepatocellular Carcinoma prediction model that integrates 7 GlnMgs, including SLC1A5, GAPDH, SLC38A1, SLC38A7, FTCD, MTHFS, and GOT2 might be utilized to predict prognosis in HCC." (PMID 37377916, 2023).
developmental delay (2 papers, 2021 to 2022). "In a girl with T cell lymphopenia, deafness, and mild developmental delay, a pathogenic variant has been detected in the FTCD gene (NM_006657.2: FTCD c.990dupG), in homozygous state with TruSight One Sequencing Panel, Illumina." (PMID 36211402, 2022). "Later, some FTCD deficiency patients with possible mild developmental delay and no hematologic abnormalities were reported." (PMID 34941873, 2021).
Down syndrome (2 papers, 2023 to 2024). "The FTCD gene is located in one of the Down syndrome critical regions on chromosome 21, i.e., 21q22.3." (PMID 39062651, 2024). "Of note, a cluster of three genes involved in the transport of folate (SLC19A1), folate metabolism (FTCD), and homocysteine elimination (CBS) is located near the Down syndrome critical region on chromosome 21 (21q22.3)." (PMID 39062651, 2024).
liver cancer (2 papers, 2023 to 2024). An epithelial or non-epithelial malignant neoplasm that arises from the liver. "The results indicated that, among various cell types within liver cancer tissues, FTCD was predominantly expressed in hepatocytes and liver malignant cells, rather than in immune cells such as T cells." (PMID 38254641, 2023).
liver cirrhosis (2 papers, 2022 to 2023). "Two diagnostic models including SOCS2, LCAT, FTCD, KRT17, PBK, and CBX2 expression were proved to accurately separate HCC from normal and liver cirrhosis samples in this study." (PMID 36159831, 2022).
diabetes (1 paper, 2025). "Formimidoyltransferase cyclodeaminase has been shown to be associated with diabetes." (PMID 41476994, 2025).
tumor (15 papers, 2021 to 2025). "The tumor diagnostic model was formulated as follows: logit (P-HCC) = -2.534 – 1.240 * SOCS2 expression level - 1.320 * LCAT expression level + 0.335 * FTCD expression level – 1.911 * KRT17 expression level + 4.422 * PBK expression level + 2.006 * CBX2 expression level." (PMID 36159831, 2022). "The tumor diagnostic model was formulated as follows: logit (P-HCC) = 6.906 - 0.494 * SOCS2 expression level - 1.250 * LCAT expression level – 0.493 * FTCD expression level + 0.602 * KRT17 expression level + 1.950 * PBK expression level + 7.243 * CBX2 expression level." (PMID 36159831, 2022). "In the clinical cohort, FTCD expression is downregulated in C1 and C4 subtypes, which is correlated with increased tumor malignancy and poorer patient outcomes." (PMID 39660131, 2024). "Pseudotime analysis of gene expression in the risk model revealed that the expression levels of FTCD and LCAT, associated with good prognosis, were higher in the late stages of tumor development." (PMID 39132167, 2024). "Additionally, FTCD was identified as a classification-specific prognostic gene with tumor-suppressing role and potential as a therapeutic target, particularly for C1 and C4 patients." (PMID 39660131, 2024). "Our investigation into FTCD’s biological roles further revealed its tumor-suppressive function." (PMID 39660131, 2024). "Thus, FTCD overexpression inhibits tumor progression and tumor immune escape in HCC via the suppression of PI3K/AKT pathway activation." (PMID 33820866, 2021). "In addition, our study identified formiminotransferase cyclodeaminase (FTCD) as a classification-specific prognostic gene with anti-tumor effects in HCC, serving as a potential therapeutic target for specific molecular classifications through bioinformatics screening and experimental evidence." (PMID 39660131, 2024). "Normal tissues exhibited higher levels of S100A9, FTCD, POF1B, IL7R, and MYO1E, whereas tumor tissues showed increased expressions of SPINK1, CXCL9, AGFG1, and IQGAP3." (PMID 41578779, 2025). "A significant increase in UCK2, HMMR, and MAGEA6 expression and a significant decrease in CXCL8, EPO, PPARGC1A, FTCD, and CFHR3 expression was observed in tumor tissues." (PMID 38694506, 2024). "The FTCD gene, a candidate tumor suppressor gene in HCC, is significantly downregulated in HCC tumor tissues." (PMID 34819088, 2021). "Regarding MTHFS (methenyltetrahydrofolate synthetase) and FTCD (formimidoyltransferase cyclodeaminase), both genes participate in the metabolism of cofactors and vitamins and are downregulated in HCC with a higher tumor stage." (PMID 36250026, 2022).
cancer (5 papers, 2016 to 2022). A tumor composed of atypical neoplastic, often pleomorphic cells that invade other tissues. "The results showed that ADA, ATP1B3, DYNC1H1 and FTCD were differently expressed in non-cancer vs. cancer tissues of different stages, in cancer tissues of stage I vs. stage II or stage I vs. stage III." (PMID 35739471, 2022). "Five hypermethylated regions were in genes previously associated with cancer (TRAP1, SLC38A3, CHRM1, EDN2, and PROX1), while six hypomethylated regions were in genes previously associated with cancer (NUMBL, ALDH1B1, FTCD, FASTKD2, FAM96A, and ARHGAP15)." (PMID 36474183, 2022). "Comparing HCC in the choline deficient model and choline supplemented model, significant methylation differences were seen in 11 genes previously associated with cancer (hypermethylation of TRAP1, SLC38A3, CHRM1, EDN2, and PROX1; hypomethylation of ALDH1B1, FTCD, FASTKD2, FAM96A, and ARHGAP15)." (PMID 36474183, 2022). "Among the 7 model genes, 4 genes were differentially expressed in HCC cells and normal para-cancer tissues, namely, ANP32B, FTCD, ADH4 and PON1." (PMID 35413690, 2022). "Moreover, among this class of targets, there are also some novel candidates whose functions in cancer have not been thoroughly investigated, including three enzymes in the histidine degradation pathway, formimidoyltransferase cyclodeaminase (FTCD), histidase (HAL), and urocanase (UROC)." (PMID 31601242, 2019).
autosomal recessive disease (1 paper, 2018). Autosomal recessive form of disease. "Out of the 3 heterozygous variants for potential autosomal recessive diseases in the offspring we found the CTSD and FTCD variants eligible for prenatal testing." (PMID 29373990, 2018).
benign tumors (1 paper, 2021). "In HCC, FTCD can also serve as a useful diagnostic biomarker to distinguish early HCC and benign tumors." (PMID 34737790, 2021).
metabolic disorder (1 paper, 2018). "Mutations in the FTCD gene on chromosome 21 have been implicated as causal for glutamate formiminotransferase deficiency, a rare metabolic disorder that affects physical and mental development." (PMID 29995946, 2018).
FTCD also shares sentences with these, for which no sentence is quoted: autoimmune disorders (1 paper); Burkitt lymphoma (1); chronic myeloid leukemia (1); deafness (1); DOCK8 immunodeficiency syndrome (1); Fanconi anaemia (1); leukemia (1); megaloblastic anemia (1); Mismatch mismatch repair cancer syndrome (1); neuromuscular disease (1); primary biliary cholangitis (1); primary sclerosing cholangitis (1).